SULF1 (sulfatase 1)
Diseases named in the same sentence as SULF1 in open-access papers (continued):
Sharing a sentence is not in itself a finding about the gene and the disease.
cancer (70 papers, 2006 to 2026). A tumor composed of atypical neoplastic, often pleomorphic cells that invade other tissues. "Several studies suggest that SULF1 is associated with the proliferation and migration of cancer cells, which lead to poor prognosis in cancers such as ovarian cancer, chondrosarcoma, and colorectal cancer." (PMID 38590118, 2025). "After forward search and backward search, we identified a set of five differentially expressed genes (LAMC2, TSPAN1, MYO1E, MYOF, SULF1) in Cancer/Normal that was optimized for diagnostic ability." (PMID 39850570, 2024). "In conclusion, these experiments indicated that cancer-associated fibroblast-derived SULF1 promoted the migration and invasion of GC cells." (PMID 38438372, 2024). "To identify the function of cancer-associated fibroblasts-derived SULF1 in GC, we knockdowned SULF1 with lentivirus (shSULF1#1 and shSULF1#2) in human primary CAFs extracted from human GC tissues." (PMID 38438372, 2024). "DNA-damage-inducible transcript 4 (DDIT4) and sulfatase 1 (SULF1) have now been shown to be associated with several types of cancer." (PMID 35155247, 2022). "The consistent increases of SULF1 in cancer tissues and their uniform association with poor survival outcomes are quite remarkable because SULF1 expression in cancer cell lines is typically low." (PMID 36428645, 2022). "The association of high SULF1 with poor survival in many cancers is quite remarkable, especially in view of the fact that the SULF1 transcript is low in most cancer cell lines." (PMID 36428645, 2022). "The general trend, however, indicates that SULF1 downregulation is associated with worse prognosis in several cancers." (PMID 32413029, 2020). "Modified expression of both sulfatases, particularly SULF-1, has been associated with different cancers." (PMID 31620357, 2019). "Therefore it seems that loss of SULF1 increases 6-O-sulfate retention at the cancer cell surface and allows the formation of a greater number of stable ternary complexes for robust signal transduction." (PMID 32413029, 2020). "Thus, the overall downregulation of SULF1 from benign to advanced forms of PCa is irrespective of stroma-derived SULF1 and is consistent with our findings that loss of SULF1 accelerates PCa cancer growth in bone metastases." (PMID 32413029, 2020). "SULF1 expression is decreased in multiple malignant lineages, and its re-expression is known to be associated with decreased signaling of heparin-binding growth factors, cell proliferation, and the invasiveness of cancer cells." (PMID 21214932, 2011). "The correlation between SULF1 and cancer risk has mainly been studied in terms of gene expression." (PMID 21214932, 2011). "Quantitative measurements indicated lower area, inverse circularity, and fewer boundary protrusions in the S1KOCAF cocultures, confirming that the Sulf1+ CAFs enhance expansion and invasion of the cancer cells into Matrigel." (PMID 41549062, 2026). "Using CRISPR/Cas9‐edited SULF1‐knockout primary HNSCC CAFs, we demonstrate that loss of SULF1 reduces fibroblast proliferation and markedly impairs cancer cell migration and invasion in vitro." (PMID 41549062, 2026). "LncRNA-NEAT1 upregulates the expression of MAPK, sex-determining region Y box 9 (SOX9), and sulfatase 1 (SULF1) by adsorbing miR-376b-3p, miR-101-3p, and miR-98-5p, respectively, promoting cancer progression." (PMID 40110044, 2025). "Pan-cancer analysis revealed that SULF1 mRNA was upregulated more than 2-fold in 16 out of the 32 cancers in the TCGA dataset." (PMID 41373732, 2025). "Heparan-6-O-endosulfatases Sulf-1 and Sulf-2 are secreted extracellular enzymes overexpressed in many types of cancer." (PMID 38825040, 2024). "Other cancers upregulate one of the SULFs (e.g., SULF1 in COAD) or the SULFs remain unchanged, but decreases, such as SULF2 in UCEC, are rare." (PMID 36428645, 2022).
cancer (continued). "Among all the cancers examined, we observed the most consistent impact of SULF1 and SULF2 in PAAD and HNSC but other cancers are affected as well." (PMID 36428645, 2022). "Following Cd exposure, the direction of the most differentially expressed genes such as SPP1, MMP3 and SULF1 in fibroid cells favored cellular migration, proliferation and cancer progression as predicted by IPA pathway analysis." (PMID 35453667, 2022). "SULF1 is a gene typical of this subtype of CAF in several cancers which supports that the CAF supply SULF1 not only in HNSC but in general; the function of SULF1 in the biology of the CAF deserves further attention." (PMID 36428645, 2022). "In MPM specimens and cell lines, SULF-1 mRNA has been found upregulated and proposed as one of the strongest candidate cancer gene." (PMID 36359323, 2022). "Our comparison of SULF mRNA in 32 TCGA tumors with the corresponding non-disease tissues from GTEx shows that SULF1 is significantly increased in 18 cancers of which 16 show >2-fold upregulation." (PMID 36428645, 2022). "Dominant expression of SULF1 in fibroblasts and its increase in HNSC tissues, in spite of low expression in the HNSC cell lines, prompted us to analyze its connection with cancer-associated fibroblasts (CAFs)." (PMID 36428645, 2022). "Based on the SULF expression in the two independent datasets (TCGA and CPTAC), we conclude that SULF1 is commonly upregulated across different cancer types while SULF2 overexpression is more restricted to certain cancer pathologies." (PMID 36428645, 2022). "High SULF1 predicts significantly lower PFI in at least 5 cancers and other malignancies, reported previously, following a similar trend." (PMID 36428645, 2022). "Our study confirms the overexpression of SULF1 and SULF2 in various cancers, which is commonly associated with poor survival outcomes; the 6-O-endosulfatases emerge as interesting targets for cancer monitoring and therapeutic intervention." (PMID 36428645, 2022). "SULF1 is one of the most consistently unregulated enzymes in HNSCC tissues even though its expression in the cancer cells is marginal." (PMID 36428645, 2022). "In the majority of cancer cells, SULF1 is downregulated, and the suppressed SULF1 expression stimulates migration, enhances invasion and promotes proliferation." (PMID 35453667, 2022). "We extended our analysis of HNSC by retrieving the RNA-seq data of 9160 patients in 32 cancer studies from the TCGA database to develop a systematic evaluation of SULF1 and SULF2 expression." (PMID 36428645, 2022). "We have strong evidence that SULF1 is supplied by CAF while SULF2 is provided primarily by the cancer cells, which has important consequences because the secreted SULF enzymes act locally due to strong non-covalent interactions with cell surfaces." (PMID 36428645, 2022). "HNSC is an interesting case because SULF2 negatively affects the survival of stage III and IV patients while the impact of SULF1 is more prominent in stage I and II cancer patients." (PMID 36428645, 2022). "Here we outlined the remarkable features of HSPGs, such as GPC1, GPC4, GPC5, SDC1, SDC2, SDC3 and HSPG2, and some HSPG-related proteins like heparanase and SULF1/2, in cancer diagnosis." (PMID 34249755, 2021). "SULF1 can promote drug-induced apoptosis of cancer cells in vitro, and inhibit tumorigenesis and angiogenesis in vivo." (PMID 35178071, 2021). "Several genes, such as EGFL6 (EGF Like Domain Multiple 6), COMP (Cartilage Oligomeric Matrix Protein), and SULF1 (Sulfatase 1), have been found to be related to multiple terms, and they are all research-proven cancer-related biomarkers." (PMID 35178071, 2021). "SULF1 is found to be involved in apicidin and doxorubicin-mediated apoptosis both in vitro and in vivo, and promotes the proliferation of carcinoma cells." (PMID 34360851, 2021).
cancer (continued). "Given that SULFs can act directly to remove 6-O-sulfate from HSPG co-receptors at the cell surface, it is reasonable to expect that cancer cells would down-regulate their SULF1 expression to escape signaling suppression." (PMID 32413029, 2020). "Although we saw a growth suppression role for stromal-derived SULF1 in the context of Wnt3A signaling, it is possible that signal transduction of other cancer-promoting pathways are concomitantly potentiated." (PMID 32413029, 2020). "Meanwhile, although delta CC mutant SULF1 revealed less pAkt protein, it also can promote cancer cell proliferation, migration and invasion." (PMID 28525382, 2017). "It showed SULF1 mRNA expression significantly increased in higher stage tumors in both UTUC (P = 0.007) and UBUC (P = 0.021), verifying the important role of SULF1 in cancer progression." (PMID 28525382, 2017). "Overall, these divergent results highlight a poor understanding of the complicated mechanisms and multifactorial implications of the SULF1 in cancers." (PMID 28525382, 2017). "Extracellular sulfatases, Sulfatase 2 (SULF2) and Sulfatase 1 (SULF1), have emerged as potential candidates for detection and therapeutic management of several cancers." (PMID 27223083, 2016). "Despite being closely related enzymes, misregulation of Sulf-1 and -2 have strikingly different consequences in cancer." (PMID 24459635, 2014). "SULF1 is often repressed in cancer cells by epigenetic mechanisms, and its re-activation interferes with cancer cell growth, invasion, and migration signaling." (PMID 24690739, 2014). "This is in line with the previous studies in cancers in which epigenetic silencing is involved in the down-regulation of Sulf1." (PMID 23325143, 2013). "It was suggested that cancers driven by WNT-1 signaling would likely be enhanced by SULF1, whereas others, where FGF2 or HGF signaling is the more significant driving mechanism, are inhibited." (PMID 23144729, 2012). "SULF1 and SULF2 are overexpressed in various human cancer types and can be associated to progression and prognosis." (PMID 21599997, 2011). "SNPs for OAS3, SULF1, DUT, and GTF2H4 were associated with HPV persistence whereas IFNG and EVER1/EVER2 SNPs were associated with progression to CIN3/cancer." (PMID 20084279, 2010). "From each region, the single most significant SNPs associated with CIN3/cancer were OAS3 rs12302655, SULF1 rs4737999, IFNG rs11177074, DUT rs3784621, DMC1 rs5757133, GTF2H4 rs2894054, EVER1/EVER2 rs9893818 (p-trends≤0.001)." (PMID 20084279, 2010). "Using scRNA-seq data, we investigated the expression of genes involved in stromal-like signature (FAP, VIM, and ITGB1); cancer-associated fibroblasts (CAFs; POSTN and ACTA2); as well as COL1A1, SULF1, TCF21, and DLK1, which were previously associated with FAP-high or FAP-low CAF phenotypes in OC." (PMID 39634630, 2024). "At the same time, high Sulf-1 in HNSCC and other cancers is associated with poor survival outcomes." (PMID 37958342, 2023). "The expressions of Sulf-1 and Sulf-2 is dysregulated in many cancers." (PMID 37958342, 2023). "Furthermore, the complete loss or reduced expression of SULF-1 has been described in cell lines derived from other cancers, which has led to suggest that SULF-1 downregulation is quite common in epithelial cancers." (PMID 36359323, 2022). "Our PDX and RNA scope experiments confirm that SULF1 is provided to the tissues by cancer-associated fibroblasts as opposed to SULF2 supplied by the cancer cells." (PMID 36428645, 2022). "The reported impact of SULF1 on cancer progression is less consistent." (PMID 36428645, 2022). "Therefore, more studies are needed to reveal the dual roles of SULF1 and its expression pattern in cancer patients." (PMID 34107956, 2021). "The level reduction of SULF1 in such environments causes increasing in 6-O-sulfate on HSPGs which subsequently leads to increasing of the fibroblast growth factor (FGF) signaling and cancer progression." (PMID 34107956, 2021).
cancer (continued). "The expression of SULF1 is stable in normal tissues but downregulated in cancer cells." (PMID 31612481, 2020). "However, more recent studies revealed over-expressed SULF1 in cancers such as pancreatic, gastric, and lung adenocarcinoma, glioma, invasive breast carcinoma, and leukemia, which exhibited protumorigenic effects." (PMID 28525382, 2017). "Evaluated by (2,3-bis-(2-methoxy-4-nitro-5-sulfophenyl)-2H-tetrazolium-5-carboxanilide) XTT, modified Boyden chamber migration and invasion assays, we identified depletion of SULF1 leaded to significant diminished cancer cell proliferation, migration, and invasion." (PMID 28525382, 2017). "In addition, expression of SULF1 or -2 has been shown to affect response to multiple cancer chemotherapeutics." (PMID 28672878, 2017). "Similarly, comprehensive reviews on Sulf1 and Sulf2 provide further details of these enzymes in different cancer types." (PMID 25105093, 2014). "It was shown that low expression of SULF1 was prevalent in these two types of cancer." (PMID 24124496, 2013). "Sulf1 has been reported to be down-regulated in several human cancers." (PMID 23325143, 2013). "Absence of Sulf1 in cancer cell lines is associated with increased cell growth, proliferation and reduced cell apoptosis." (PMID 23325143, 2013). "In addition to cancer, Sulf1 was also studied with respect to normal development including neural, muscular, vascular and skeletal development." (PMID 23325143, 2013). "Notably, SULF1 in this region has been suggested to modulate signaling by heparin-binding growth factors, and downregulation represents a novel mechanism by which cancer cells can enhance growth factor signaling." (PMID 22675446, 2012). "This supports our hypothesis that SULF1+ CAF alter the local microenvironment by creating invasive tracks through which the cancer cells migrate, while SULF2, originating from the cancer cells, promotes cancer cell growth more than it affects the local invasion." (PMID 41549062, 2026). "SULF1 is a member of the sulfatase family, which regulates the sulfation of heparan sulfate proteoglycans and has been implicated in the prognosis of various types of cancer for both positive and negative prognostic impact." (PMID 41373732, 2025). "The target pathways related to the effect of SULF1 include hedgehog, Wnt, and multiple heparan sulfate-dependent receptor tyrosine kinase pathways, which may prove to be an important method to prevent and treat cancer." (PMID 35433683, 2022). "However, our analyses of HNSC and analyses of other cancers show that SULF1 is high in cancer tissues and supplied by the CAF, a cell type associated with cancer invasion, metastasis, and the escape from immune surveillance and so far overlooked in the cancer biology of the SULF enzymes." (PMID 36428645, 2022). "Moreover, cancer cell proliferation and migration could be inhibited by re‐expression of SULF1 (Lai, Sandhu, Shire, & Roberts, 2008)." (PMID 31612481, 2020). "In considering Sulf1 or Sulf2 as drug targets, the main consideration is the increasing evidence implicating the Sulfs in cancer and whether these are responsible for augmenting cancer cell growth or inhibiting it." (PMID 25105093, 2014). "Furthermore, with regards of the opposing activities of Sulf-1 and -2 in the development of many cancers, it could be of high interest to design inhibitors discriminating these two isoforms." (PMID 24459635, 2014). "Here we demonstrate that SULF1‐KO in primary HNSCC CAF significantly impairs cellular motility and invasive potential of cancer cells." (PMID 41549062, 2026). "Pan-cancer analysis of TCGA and CPTAC (proteomics) data shows that SULF1 and SULF2 are oncogenic in a number of human malignancies and associated with poor survival outcomes." (PMID 36428645, 2022). "Proteogenomic analysis of the TCGA and CPTAC datasets conclusively documents a significant elevation of SULF1 and SULF2 in multiple cancer tissues compared with adjacent or normal counterparts." (PMID 36428645, 2022).
cancer (continued). "In this study, the transcript for the extracellular sulfatase SULF-1 (SULF-1), which modifies heparan sulfate and can influences cancer growth and spread, has been found overexpressed in MPM." (PMID 36359323, 2022). "This is uniformly corroborated by protein increases and at least six cancers (BRCA, HNSC, KIRC, LUSC, LUAD, PAAD) consistently upregulate both SULF1 and SULF2." (PMID 36428645, 2022). "After detection of CSC features, the RNA expression levels of DDIT4, SULF1, TPTEP1 and miRNAs (miR-181d-5p and miR-148b-3p) were measured using RT‐qPCR in colorectal CSC-enriched spheroids and HT-29 cancer cells." (PMID 34107956, 2021). "SULF1 and SULF2 are dysregulated in a number of tumors, but their role in cancer progression is still controversial." (PMID 34249755, 2021). "The levels of SULF1 (Fig 2A1–2A3) and HSPG2 (Fig 2B1–2B3) transcripts were highest in the cells in the stroma between cancer nests." (PMID 32413029, 2020). "Despite functional similarities between SULF1 and SULF2, the roles of these two enzymes in the pathogenesis of cancer seem to diverge." (PMID 28672878, 2017). "Many researchers also demonstrated the ability of SULF1 and SULF2 in editing post-synthetic sulfation status of 6-O-S from HSPGs, and thus the implication and potential roles of SULFs in malignancies were extensively investigated." (PMID 28525382, 2017). "Transcriptional patterns of HS-metabolic enzymes (EXT1, EXT2, NDST1, NDST2, GLCE, 3OST1/HS3ST1, SULF1, SULF2, HPSE) were determined in normal, benign, and cancer human prostate tissues and cell lines (PNT2, LNCaP, PC3, DU145)." (PMID 24782989, 2014). "When PanIN samples were compared to PDACs, the most commonly up-regulated genes in the cancers were POSTN, COL1A2, SULF1, FN1, IGHM, VCAN and XIST, and these down-regulated were PGC and PPY." (PMID 23372777, 2013). "The secretion of SULF1 and SULF2 raises the possibility for cancer cells to remodel the extra-cellular matrix in their environment, thereby affecting their development and/or the neighbouring host cells." (PMID 21599997, 2011). "The approach has led to the recognition of a number of cancer-related putative targets for the EMCIT technology, including prostatic acid phosphatase (PAP), prostate-specific antigen (PSA), and sulfatase 1 (SULF1)." (PMID 16857057, 2006). "Migration of the cancer cells is stimulated by the conditioned media of the HNCAF37 in a SULF1‐dependent manner, and invasion of the cancer cells into Matrigel in a spheroid coculture model is abrogated by the SULF1 KO in the HNCAF37 cells." (PMID 41549062, 2026). "In contrast, CBX3, CHN1, SULF1 and VDAC1 were significantly elevated in SKCM compared to HD samples, while EDIL3 and PALLD demonstrated significantly lower expression levels in the cancer samples." (PMID 41350567, 2025). "Additionally, we investigated the expression of SULF1 in normal tissues and primary tumors using the UALCAN cancer database." (PMID 38590118, 2025). "Delineation of SULF1 expression in distinct epithelial cancer types has revealed the expression was completely lacked or markedly decreased in various cancer cell lines, suggesting that reduction of SULF1 is a general feature among epithelial cancers." (PMID 36622753, 2023). "Previous studies showed that SULF1 and SULF2 are upregulated in several cancers." (PMID 36428645, 2022). "According to the previous literature, SULF1 and SULF2 may have opposing effects in cancer progression despite similar structures and activities." (PMID 28525382, 2017). "Of interest, SULF1 also leaded to significantly increased cancer cell migration and invasion, which were not depleted by delta CC mutation." (PMID 28525382, 2017). "Although SULF1 appears upregulated in gastric and other cancers, this gene was not detectable in TR146 cells using qRT-PCR." (PMID 26883112, 2016). "Sulf-1 is typically not expressed in cancer cell lines and its overexpression may suppress cell growth." (PMID 37958342, 2023).